TGFA (transforming growth factor alpha)
Diseases named in the same sentence as TGFA in open-access papers (continued):
Sharing a sentence is not in itself a finding about the gene and the disease.
glioma (23 papers, 2011 to 2025). A benign or malignant brain and spinal cord tumor that arises from glial cells (astrocytes, oligodendrocytes, ependymal cells). "The TGFA gene, located on chromosome 2, demonstrated significant associations with glioma across several brain regions—including the caudate basal ganglia, cortex, and hypothalamus—based on FUSION analysis results." (PMID 41267963, 2025). "MR supported a potential causal effect of TGFA on glioma risk, yielding statistically significant associations (p < 0.05)." (PMID 41267963, 2025). "It is important to acknowledge that TGFA has previously been implicated in gliomas, largely through its role as a ligand of EGFR." (PMID 41267963, 2025). "Unlike these studies, our work combined diverse omics methodologies—such as TWAS, UTMOST, MAGMA, FUSION, and Bayesian colocalization—to map glioma risk genes, with a focus on TGFA as a novel risk factor in the caudate basal ganglia, cortex, and hypothalamus." (PMID 41267963, 2025). "By contrast, our study is the first to integrate large-scale GWAS, multi-tissue eQTL datasets, and cross-tissue transcriptomic analyses to establish TGFA as a glioma susceptibility gene in human populations." (PMID 41267963, 2025). "TGFA showed significant glioma associations across brain tissues and causal relationships via Mendelian randomization (OR: 1.27–1.39), supported by Bayesian colocalization." (PMID 41267963, 2025). "Mendelian randomization revealed a connection between higher TGFA expression and increased glioma risk, whereas colocalization analysis revealed common causal variants." (PMID 41267963, 2025). "Through cross-tissue TWAS coupled with rigorous validation, we identified TGFA as a previously unreported glioma risk locus." (PMID 41267963, 2025). "A tiered analytical pipeline—incorporating cross-tissue transcriptome-wide association via UTMOST, tissue-specific TWAS with FUSION, and MAGMA-based gene prioritization—uncovered Transforming Growth Factor Alpha (TGFA) as a novel glioma risk locus." (PMID 41267963, 2025). "Emerging evidence suggests that TGF-α/EGFR signaling plays a pivotal role in tumor cell proliferation, differentiation, and survival, raising the possibility that TGFA itself may represent a novel glioma susceptibility locus and therapeutic target." (PMID 41267963, 2025). "Our discovery of TGFA as a glioma susceptibility gene adds to the growing body of research by connecting cross-tissue transcriptome connections to functional validation and therapeutic repurposing, thereby expanding the molecular framework of gliomagenesis for translational application." (PMID 41267963, 2025). "TGFA is a novel glioma susceptibility gene with subtype-specific expression." (PMID 41267963, 2025). "TGFA expression patterns mirrored genetic associations, showing marked upregulation in WHO grade 2–3 gliomas versus grade 4 and in 1p/19q codeleted tumors across TCGA, CGGA, and institutional cohorts." (PMID 41267963, 2025). "This mechanistic insight provides a rationale for reconsidering irinotecan not as an empirical chemotherapeutic, but rather as a biomarker-guided therapeutic candidate in TGFA-driven glioma subtypes." (PMID 41267963, 2025). "In both the TCGA and CGGA cohorts, WHO grade II and III gliomas had significantly higher TGFA expression levels than grade IV tumors (p < 0.0001)." (PMID 41267963, 2025). "TGFA expression was assessed in glioma samples via public genomic repositories and immunohistochemistry." (PMID 41267963, 2025). "Prognostic evaluation of glioma patients was performed via IHC staining of TGFA in surgically resected tissues." (PMID 41267963, 2025). "EGFR alterations represent one of the most common molecular hallmarks of gliomas, however, the contribution of its upstream ligand TGFA to gliomagenesis has remained largely unexplored." (PMID 41267963, 2025). "Elevated TGFA expression occurred in WHO grade 2/3 gliomas and 1p/19q co-deleted tumors, validated by immunohistochemistry." (PMID 41267963, 2025).
glioma (continued). "HBEGF and TGFA serve as established ligands for EGFR, and their intricate interplay triggers a cascade of signaling pathways implicated in glioma development." (PMID 39722126, 2024). "Glioma-associated DEGs CD244, IL21, RET, TGFA were up-regulated and AQP9, IGFBP2, EGFR, SOX9 were down-regulated specifically in the rat." (PMID 29352201, 2018). "To assess therapeutic benefits or unintended effects of TGFA as a glioma drug target and evaluate off-target pleiotropy beyond MR–Egger intercept findings, we performed gene-level PheWAS using 17,361 binary and 1,419 quantitative traits from the AstraZeneca PheWAS Portal." (PMID 41267963, 2025). "Notably, TGFA levels were markedly elevated in WHO grade 2 gliomas compared to grades 3–4 and in tumors with 1p/19q co-deletion versus non-codeleted cases, aligning with TCGA and CGGA database findings." (PMID 41267963, 2025). "TGFα stimulates the growth of glioma cells through the phosphorylation of ERK1/2." (PMID 22864984, 2012). "Likewise, TGFα downregulation, a mitogenic protein, incriminates the agonistic role of GA-T0 in forming autocrine looping, supporting the antiproliferation of human glioma." (PMID 34359676, 2021). "The CTD database (see text footnote 6, respectively) was queried for TGFA drug targets, revealing 40 FDA-approved drugs with potential for treating glioma among 242 interacting chemicals." (PMID 41267963, 2025). "It is well known that wild-type EGFR ligands such as transforming growth factor-alpha (TGF-alpha) and heparin-binding EGF (HB-EGF) are often increased in glioblastoma leading to an autocrine loop resulting in the autonomy growth of glioma cells." (PMID 33435537, 2021). "In renal carcinoma and glioma, ETS1 promotes cell proliferation by up-regulating TGFα expression; in hepatocellular carcinoma, ETS1 promotes cell proliferation by activating the expressions of cyclin E and cyclin-dependent kinase 2 (CDK2)." (PMID 34889689, 2021). "The first link between EGFR activity and VEGF expression was reported almost 20 years ago when it was shown that two EGFR ligands, EGF and TGFα, stimulated the expression of VEGF in glioma cells and in hyperproliferative keratinocytes." (PMID 27806094, 2016). "Additionally, a search of the ChEMBL database revealed a drug targeting TGFA, revealing 154 FDA-approved drugs with potential for treating glioma among 464 drugs." (PMID 41267963, 2025). "In addition, other EGF-like ligands such as TGFα and HB-EGF are involved in self-activation loops in gliomas producing ErbB1." (PMID 24330607, 2013). "Similarly, tumors harboring 1p/19q co-deletion demonstrated significantly upregulated TGFA expression compared to non-codeleted gliomas in these datasets (p < 0.0001)." (PMID 41267963, 2025). "Five out of the ten top hub nodes from general glioma networks from StringDB and BioGRID are matching genes containing erb-b2 receptor tyrosine kinase 2 (HER2), erb-b2 receptor tyrosine kinase 4 (HER4), cyclin D3 (CCND3), TEK tyrosine kinase (TEK), and transforming growth factor alpha (TGFA)." (PMID 31952211, 2020). "Importantly, a subset of these human-derived cytokines that included CXCL10, IL-33, CXCL8, KITLG, CCL2, and TGFα were not secreted or secreted at very low levels in vitro by BT147 cells, suggesting that the increased secretion was the result of a glioma–host cell interaction within the brain." (PMID 33020472, 2020).
prostate carcinoma (22 papers, 1990 to 2025). A carcinoma that arises from epithelial cells of the prostate gland. "miR-152 normally targets oncogenic pathways (e.g., it can target DNA methyltransferase 1 and TGFα) and that its loss has been linked to increased proliferation, invasion, and therapy resistance in prostate cancer." (PMID 41462933, 2025). "Markedly, our data demonstrate that the activated EGFR signaling-induced autocrine AREG, EREG, and TGFA expression in Ras-mutated prostate cancer cells is associated with a down-regulation in miR-203 expression level in an EGF-dependent manner." (PMID 25004126, 2014). "Overexpression of miR-152 in PC-3 and DU145 cells effectively suppressed the invasive and migratory abilities of prostate cancer cells by targeting TGFα, a key player in EGFR signaling." (PMID 39606232, 2024). "In bone metastases of prostate cancer, by contrast, TGFα, PDGF, and interleukins were shown to play a predominant role in AKT activation." (PMID 34064589, 2021). "In prostate cancer, miR-152 reduced the prostate cancer cells’ migratory and invasive capabilities through directly targeting TGFα." (PMID 34680020, 2021). "The results from the analysis of clinical specimens suggest that decreasing miR-203 and increasing of EGFR ligands, (EREG and TGFA) expression are correlated with prostate cancer progression." (PMID 25004126, 2014). "Interestingly, transforming growth factor α (TGFα) is able to stimulate the RANKL expression selectively in late-stage prostate cancer cells and, thus, induces osteoclast differentiation." (PMID 34064589, 2021). "Given the critical role of Ras mutation-induced EGFR signaling activation in prostate cancer progression, we hypothesized that EGF-induced autocrine AREG, EREG, and TGFA expression might be directly mediated by miR-203 in RasB1 cells." (PMID 25004126, 2014). "Moreover, we observed a high expression of AREG, EREG, and TGFA in tumors that had higher KRAS oncogenic response gene signatures in the human prostate cancer dataset." (PMID 25004126, 2014). "Serum-free media conditioned by the androgen insensitive human prostate cancer cell line DU145 showed immunological transforming growth factor-alpha (TGF alpha) activity, as well as competing activity in epidermal growth factor (EGF) radioreceptor assays (RRA)." (PMID 2223575, 1990). "In addition, miR-152 can inhibit migration and invasion by targeting TGFA in prostate cancer." (PMID 34322376, 2021). "By inhibiting TGFα-EGFR signaling, miR-152 also downregulated downstream genes MMP2 and MMP9, further suppressing the invasive and migratory potential of prostate cancer cells in vitro." (PMID 39606232, 2024). "Previous studies observed that reduced TGFα induced own-regulation of MMP-2 and exhibited low invasive ability in prostate cancer." (PMID 26843615, 2016). "In prostate cancer patients, our data showed that miR-203 levels were inversely correlated with the expression of two EGFR ligands, EREG and TGFA, and an EGFR dependent gene signature." (PMID 25004126, 2014). "Mechanistically, TGFα, a member of the epidermal growth factor (EGF) family, was shown to bind to the EGFR leading to a significant AKT activation in the late-stage prostate cancer cells, whereas stimulation of early-stage prostate cancer cells with EGF diminishes AKT activation." (PMID 34064589, 2021).
hepatocellular carcinoma (19 papers, 1993 to 2025). A malignant tumor that arises from hepatocytes. "In AEG-1-C75S liver, activation of cell proliferation and invasion were detected which were associated with activation of oncogenic MAP2K4, MAP3K1, TGFA, NRF2, and STAT3 signaling ultimately contributing to hepatocellular carcinoma." (PMID 38677511, 2024). "Growth factor receptor ERBB3 and transforming growth factor alpha (TGF-α) were recently shown to act as compensatory survival factors that increased after c-Met inhibition in hepatocellular carcinoma cells." (PMID 27443843, 2016). "LGR is induced by interleukin-6, interleukin-1-beta and transforming growth factor-alpha in hepatoma cells, and is over-expressed in livers of the mice challenged by lipopolysaccharide, rendering it an acute phase protein." (PMID 24066001, 2013). "Phosphorylation of c-Met by TGF-α/EGFR (receptor of TGFα) was found in several epithelial derived tumor cell lines such as human hepatoma cell lines and epidermoid carcinoma cell line, and subsequently leading to its activation." (PMID 23320251, 2012). "We have previously studied specific behaviours in transgenic male CD-1 MT42 mice, which overexpress the gene encoding human transforming growth factor alpha (TGF alpha) in multiple tissues, and which develop a high incidence of spontaneous hepatocellular carcinoma." (PMID 8494695, 1993). "For hepatocellular carcinoma (HCC), silibinin induces apoptosis by downregulating TGFα-EGFR autocrine loops and inhibiting survival pathways." (PMID 40650040, 2025). "HepG2 cells were derived from a hepatocellular carcinoma, while AML12 cells were derived from the livers of transgenic mice overexpressing transforming growth factor alpha." (PMID 34199599, 2021).
cervical carcinoma (17 papers, 2011 to 2025). A carcinoma arising from either the exocervical squamous epithelium or the endocervical glandular epithelium. "E6 suppresses YAP degradation and promotes nuclear YAP localization, thereby increasing growth-related genes, including amphiregulin (AREG) and transforming growth factor alpha (TGFA), which encode TGF-α, in cervical cancer." (PMID 36294681, 2022). "Activated YAP triggers the amplification of EGFR, AREG and TGFα, and therefore a positive loop is formed that promotes cervical cancer progression." (PMID 33467099, 2021). "EGFR ligands such as amphiregulin and TGFα were upregulated by IL-6 via an EGFR-dependent pathway of autocrine stimulation in human cervical carcinoma cells and virus-immortalized cells." (PMID 32709896, 2020). "Finally, in order to verify the function of TGFA, the expression of TGFA was down‐regulated by stable transfection of shRNA using the cervical cancer cell lines HeLa and SiHa." (PMID 38152044, 2024). "The results showed that TGFA was highly expressed in cervical cancer tissues and cells." (PMID 38152044, 2024). "TGFA knockdown can inhibit the proliferation, migration and invasion of cervical cancer cells." (PMID 38152044, 2024). "In conclusion, TGFA plays an important role in the occurrence and development of cervical cancer." (PMID 38152044, 2024). "Therefore, TGFA may become a new target for cervical cancer treatment." (PMID 38152044, 2024). "Immunohistochemical staining revealed TGFA expression in 16 normal cervix, 6 cases of cervical precancerous lesions (CIN‐III) and 42 cases of cervical cancer samples." (PMID 38152044, 2024). "The protein–protein interaction study indicates the interacting partners of EREG, and they were EGF, TGFA, GRB2, and HRAS, and most of them regulate cervical cancer." (PMID 34439555, 2021). "Activation of YAP1 in cervical cancer cells significantly stimulated the expression of EGFR and its ligands TGFα and AREG." (PMID 30840887, 2019). "In turn, TGFα and AREG, via EGFR signaling, suppressed the Hippo pathway and activated YAP protein (dephosphorylated LATS1, MOB1, and YAP1) to promote cervical cancer cell growth." (PMID 30840887, 2019). "It is of interest to note that, by binding and activating EGFR, both AREG and transforming growth factor α (TGFα) induce the dephosphorylation of LATS1, MOB1 and YAP in the Hippo signaling pathway, thus activating YAP that drives the proliferation and migration of cervical cancer cells." (PMID 33467099, 2021).
gastric cancer (17 papers, 1995 to 2025). A primary or metastatic malignant neoplasm involving the stomach. "The SEC11A gene encodes the signal peptidase complex 18, which contributes to malignant progression via promotion of transforming growth factor alpha secretion in gastric cancer." (PMID 39002029, 2024). "The expression of AREG, EGF, HB-EGF and TGFα in gastric tumours and body fluids of gastric cancer patients has been analysed in multiple studies." (PMID 27933395, 2017). "In this study, we analysed the involvement of the HER receptor ligands amphiregulin (AREG), epidermal growth factor (EGF), heparin-binding epidermal growth factor (HB-EGF) and transforming growth factor alpha (TGFα) in the responsiveness of gastric cancer cell lines to cetuximab and trastuzumab." (PMID 27933395, 2017). "We analysed the level of HB-EGF and TGFα in our panel of gastric cancer cell lines." (PMID 27933395, 2017). "For our analyses, we concentrated mainly on AREG, HB-EGF and TGFα, as previous results from our group had shown the absence of EGF secretion in gastric cancer cell lines." (PMID 27933395, 2017).
glioblastoma (15 papers, 2012 to 2024). The most malignant astrocytic tumor (WHO grade IV). "The production of PDGF (platelet-derived growth factor) and TGFα (tumor growth factor α) by glioblastomas and sarcomas, respectively, are two illustrative examples." (PMID 23285163, 2012). "TGFα did not rescue the transfilter deficiency of glioblastoma U251 cells with compromised TMED9 function, used here as outlier controls." (PMID 31253868, 2019). "A number of reports indicated paracrine secretion as paramount to glioblastoma growth, with ligands such as TGFα, IL-6, ΙL-8, HGF and heparin binding EGF playing central role, further supporting the hypothesis." (PMID 27004406, 2016). "EGFR’s most important ligands in glioblastoma include epidermal growth factor (EGF) and transforming growth factor-alpha (TGF-α)." (PMID 38928445, 2024). "Genes that show higher expression in astrocytoma compared to glioblastoma were CX3CL1, CSF1 (MCSF), CCL3 (MIP1α), CCL4 (MIP1β), TGFα, FLT3LG, CXCL5, CCL19 while KITLG (SCF) and NGF were equally expressed in the two tumor types." (PMID 35301393, 2022). "Initial discovery and extensive studies of the epidermal growth factor (EGF) and transforming growth factor alpha (TGF-α), as well as the platelet-derived growth factor (PDGF) family, revealed their presence in glioblastoma cell cultures and tissues." (PMID 22509804, 2012).
melanoma (15 papers, 1989 to 2023). A malignant, usually aggressive tumor composed of atypical, neoplastic melanocytes. "Finally, SPRY2 (Bladder), CBL (Endometrial), TGFA (Melanoma) and GAB2 (Non-small cell lung) genes have high risk rate and low survival rate." (PMID 34764329, 2021). "DEG analysis further revealed upregulation of genes SPRY2 (Bladder), and GAB2 (Non-small cell lung) and downregulation of genes CBL (Endometrial), TGFA (Melanoma) were associated with low survival rate and high risk of death as measured by survival probability and AUC score." (PMID 34764329, 2021). "After Survival Analysis we concluded that four genes (SPRY2-for Bladder cancer, CBL-for Endometrial cancer, TGFA-for Melanoma and GAB2 for Non-small cell lung cancer) were the Biomarkers for Nitroglycerin." (PMID 34764329, 2021). "Interestingly, it was recently shown that TGFA belongs to the genes most strongly upregulated in SK-MEL-28 MITF-knockout melanoma cells compared to their controls." (PMID 33916908, 2021). "Here, we describe that the transcription factor NRF2, the master regulator of the oxidative and electrophilic stress response, mediates the expression and activation of EGFR in melanoma by elevating the levels of EGFR as well as its ligands EGF and TGFα." (PMID 33916908, 2021). "When we increased MITF levels in UACC-62 melanoma cells with a doxycycline-inducible expression vector, TGFA was repressed on RNA level, and TGFα secretion, measured by ELISA, was clearly reduced." (PMID 33916908, 2021). "In contrast, regulation of EGFR and TGFA occurs by an indirect mechanism, which is enabled by the ability of NRF2 to block the activity of the melanocytic lineage factor MITF in melanoma." (PMID 33916908, 2021). "MITF and EGFR are expressed in melanoma cells in a mutually exclusive manner, and MITF was described previously to suppress TGFA expression." (PMID 33916908, 2021). "These are EGFR, ERRFI1, IL6, JAK2, PLXNC1, RGL3 which were found to be upregulated and CBL, CDC42, PIK3R3, STAT3, UBE2D2 and YWHAZ which were found to be downregulated; Melanoma has PLXNC1 as upregulated and TGFA as downregulated gene." (PMID 34764329, 2021).